RAD51 (RAD51 recombinase)
Diseases named in the same sentence as RAD51 in open-access papers (continued):
Sharing a sentence is not in itself a finding about the gene and the disease.
cancer (continued). "This suggests that the DNA-PKcs inhibitor NU7026 and Rad51 inhibitor B02 sensitized cancer cells to the C ion irradiation via suppression of the NHEJR and HRR pathways, respectively." (PMID 26553138, 2015). "RAD51 recombinase activity plays a critical role for cancer cell proliferation and survival, and often contributes to drug-resistance, therefore been proposed as an alternative and supplementary strategy for cancer treatment." (PMID 25749979, 2015). "The amount of overexpression of Rad51 correlates with resistance to cancer treatment as well as degree of cancer advancement." (PMID 26111183, 2015). "While we found significantly decreased expression of multiple NHEJ and HR repair proteins in HPV+ HNSCC cell lines, BRCA1 and RAD51, two key HR proteins often identified as the culprits in other HR-defective cancers, appear relatively unaffected." (PMID 26336991, 2015). "Next, we determined if the protein interaction between IRS-1 and RAD51 in our cancer cells was modified after IGF-1Rki treatment using immunoprecipitation." (PMID 26510816, 2015). "For instance, in some cancer cells under hypoxic conditions, HR is downregulated at the stage of RAD51 loading on chromatin, which is downstream of resection." (PMID 25826455, 2015). "Elevated expression of RAD51 protein has been observed in a wide variety of cancers suggesting that overexpression of RAD51 confers advantages to tumor cells." (PMID 25539919, 2015). "XRCC2 and XRCC3 proteins are structurally and functionally related to RAD51, which plays an important role in the homologous recombination, the process being frequently involved in cancer transformation." (PMID 24728564, 2015). "The association between the C allele of RAD51 gene rs1801320 polymorphism and the age and PSAT serum level of the cancer patients was analyzed." (PMID 26339569, 2015). "Because RAD51 is an integral component of the cellular DNA damage response, RAD51 suppression can sensitize cancer cells to DNA-damaging drugs." (PMID 26369335, 2015). "As HR machinery components have now become crucial targets for cancer treatment, there is a widely observed correlation between expression levels of RAD51 and resistance to therapeutic drugs." (PMID 25539919, 2015). "The E2F site can bind various members of the E2F family, but since E2F1 and RAD51 are often dysregulated in cancer, we focused on the effect of E2F1 on the bidirectional promoter." (PMID 26230935, 2015). "PTEN in the nucleus then acts as a positive transcriptional regulator of Rad51 paralogs, which are essential for the maintenance of the HR DNA repair system, which can protect cancer cells from temozolomide-induced cytotoxicity." (PMID 25061500, 2014). "We also utilized animal models to show that RAD51 is required for metastasis and discovered that RAD51 is a potential transcriptional co-factor of c/EBPβ and supports metastatic expansion of cancer cells via regulating changes in gene expression." (PMID 24811120, 2014). "This is consistent with the previous findings that the levels of partner HR protein Rad51, as well as HR repair efficiency, are up-regulated in cancer cells." (PMID 24742710, 2014). "Recent research on Rad51, the essential recombinase required for homologous recombination (HR), reveals that the promoter of Rad51 is highly expressed in a panel of cancer cells in comparison to a set of normal cells." (PMID 24742710, 2014). "In contrast, rapid Rad51 expression was induced in cancer cells after DNA damage and delay of cell cycle restoration was not as severe as in normal cells." (PMID 25334017, 2014). "In order to identify alternative promoters with high specificity to cancer cells we examined the tumor specificity of Rad51 paralogs Rad51B, Rad51C, Rad51D and Rad52." (PMID 24742710, 2014).
cancer (continued). "Given strong correlation between RAD51 overexpression and cancer, RAD51 has been recognized as an important target for novel anti-cancer therapies." (PMID 24971740, 2014). "When Rad51 promoter was truncated to 2 to 3 kb, differential in promoter activity between cancer and normal cells was reduced to 60-fold or less." (PMID 24742710, 2014). "Our current data demonstrate that use of RAD51-specific small molecule inhibitor represents a feasible strategy of a combination anti-cancer therapy." (PMID 24971740, 2014). "Rad51 expression affects both chemo- and radiosensitivity in many cancers; however, its role in ESCC is unclear." (PMID 24065387, 2014). "We further revealed that Spironolactone impairs Rad51 foci formation, sensitizes cancer cells to DNA damaging agents, to Poly (ADP-ribose) polymerase (PARP) inhibitors and cross-linking agents and inhibits tumor growth in xenografts, in mice." (PMID 24682826, 2014). "Here, we wanted to exploit this cancer vulnerability by developing specific small molecule inhibitors of RAD51, a central HR protein." (PMID 24971740, 2014). "The stabilization of the cancer genome means that deregulated RAD51 is promoting aberrant DNA repair that allows advantageous mutations beyond those required for primary tumors." (PMID 24811120, 2014). "This differential between cancer and normal cells is even greater for the Rad51 promoter, when a 6.5 kb promoter fragment is used." (PMID 24742710, 2014). "Targeting RAD51 has thus been proposed as a potential anti-cancer treatment, and downregulation of RAD51 by siRNA has been shown to selectively increase the chemotherapeutic sensitivity of human cancer cells relative to normal cells." (PMID 25401086, 2014). "Subsequent knockdown of RAD51 repressed cancer cell migration in vitro and reduced primary tumor growth in a syngeneic mouse model in vivo." (PMID 24811120, 2014). "Rad51 expression is elevated in a wide range of cancers and Rad51 promoter has been used to transcriptionally target tumor cells, however, a large size of Rad51 promoter limits its application for gene therapy." (PMID 24742710, 2014). "Directly targeting RAD51 and attenuating the deregulated RAD51 activity has therefore been proposed as an alternative and supplementary strategy for cancer treatment." (PMID 23341130, 2013). "The therapeutic potential of exosome-mediated siRNA delivery was demonstrated in vitro by the strong knockdown of RAD51, a prospective therapeutic target for cancer cells." (PMID 24245560, 2013). "By exploiting the ‘addiction’ to RAD51 of certain cancers that are under genotoxic stresses, we are optimistic that a therapeutic window can be available for tumor-specific killing." (PMID 23341130, 2013). "We can assume that exosomes effectively deliver siRNA into the target cells in vitro, causing selective genes silencing and leading to reproductive cancer cell death by knockdown of RAD51 recombinase." (PMID 24245560, 2013). "RAD51 recombinase activity plays a critical role for cancer cell proliferation and survival, and often contributes to drug-resistance." (PMID 23341130, 2013). "Here we describe the development of a RAD51 specific small molecule inhibitor for potential cancer treatment." (PMID 23341130, 2013). "The results show that exosomes effectively delivered the siRNA against RAD51 into the target cells, causing selective genes silencing and leading to reproductive cancer cell death by knockdown of RAD51." (PMID 24245560, 2013). "Although IBR2 has shown a promising anti-tumor activity in the current cancer model, one should be aware that RAD51 is also an essential factor for normal cells." (PMID 23341130, 2013). "Consistent with this idea, prior studies have shown that depletion of RAD51, using small interfering or antisense RNAs, sensitizes cancer cells to IR and promotes cell death." (PMID 23341130, 2013).
cancer (continued). "Summing up the data, we can assume that exosomes effectively delivered the siRNA into the target cells, causing selective genes silencing and leading to reproductive cancer cell death by knockdown of RAD51." (PMID 24245560, 2013). "We demonstrated that in most cancer cell types studied the decrease in the RAD51 protein level induced cell accumulation in S and G2 phases of the cell cycle and ultimately led to the massive reproductive cell death." (PMID 24245560, 2013). "RAD51 135G>C can modify promoter activity and the penetrance of BRCA1/2 mutations, which plays vital roles in the etiology of various cancer." (PMID 24040396, 2013). "Recently, cytoplasmic AEG-1 has been identified as a RNA-binding protein, which provides survival advantage to cancer cells under conditions of stress by blocking Rad51 nuclear accumulation." (PMID 22884085, 2012). "For example, imatinib (Gleevec), which inhibits c-Abl tyrosine kinase, can efficiently reduce the expression of RAD51 in cancer cells and confer radiosensitivity." (PMID 21858113, 2011). "The level of RAD51 mRNA showed a significant reduction in both cancer cell lines after treatment with berberine, suggesting that the downregulation of RAD51 was probably due to decreased transcription of RAD51 mRNA." (PMID 21858113, 2011). "Our study sheds light on the functional relationship of RAD51 and every known RAD51 mediators for the first time, and thereby significantly contributes to the development of effective anti-cancer therapies." (PMID 21779174, 2011). "In this report, we performed a more comprehensive analysis of the Rad51 promoter in a broad range of cell lines, including both cancer cells and primary cells." (PMID 22174876, 2011). "Expression of the DNA repair gene, Rad51, has been shown to be upregulated in many cancers, especially higher grade chemoresistant and radioresistant tumors." (PMID 22174876, 2011). "The understanding of the function of individual RAD51 mediators and their functional interactions will contribute to the accurate prediction of anti-cancer therapy efficacy." (PMID 21779174, 2011). "Phenyl hydroxamic acid PCI-24781, a histone deacetylase inhibitor that has a radiosensitizing effect on cancer cells, also acts by downregulating RAD51." (PMID 21858113, 2011). "This demonstrates the robust ability of the Rad51 promoter to drive expression of a cytotoxic transgene in cancer cells." (PMID 22174876, 2011). "Several previous studies also showed that some anti-cancer drugs render cancer cells radiosensitive and chemosensitive by downregulating RAD51 and consequently impairing homologous recombination repair in cancer cells." (PMID 21858113, 2011). "Our experiments defined a small (447 bp) element from the Rad51 promoter that supports cancer specific transcriptional activity, and is sufficiently compact to allow its use in DNA delivery systems where transgene capacity is limited." (PMID 22174876, 2011). "The radiosensitizing effect of berberine was attenuated in cancer cells overexpressing exogenous RAD51." (PMID 21858113, 2011). "Expression of an adenovirally-vectored luciferase reporter gene from the Rad51 promoter was up to 50 fold higher in cancer cells than in normal cells." (PMID 22174876, 2011). "This makes the Rad51 promoter a very attractive candidate for use in anti-cancer therapies especially when coupled with the efficient transduction capabilities of viral vectors." (PMID 22174876, 2011). "We demonstrated for the first time that berberine can efficiently downregulate RAD51 expression in cancer cells in conferring radiosensitivity." (PMID 21858113, 2011).
cancer (continued). "We have used classical molecular dynamics (MD) simulations to explore the interface between RAD51 and the different BRC repeats and also their cancer-associated mutations at a critical interaction hotspot." (PMID 21789034, 2011). "These families included a subset of families where cancer-affected individuals were shown to share a haplotype around the RAD51 locus." (PMID 16762046, 2006). "Single‐cell sequencing data from CancerSEA revealed a significant positive correlation between RAD51 expression and multiple malignant phenotypes, including cell proliferation, cell cycle progression, DNA damage repair and invasion, across diverse cancer types." (PMID 41350246, 2025). "However, CACClnc-mediated regulation of RAD51 splicing disrupts this process, facilitating homologous recombination and promoting oxaliplatin resistance in cancer cells." (PMID 40781643, 2025). "RAD51, a critical protein involved in DNA homologous recombination repair, is vital for maintaining genomic stability and is frequently overexpressed in various cancers." (PMID 41515956, 2025). "Its dysregulation may contribute to genomic instability in cancer, making RAD51 inhibition a promising therapeutic strategy." (PMID 40949156, 2025). "However, nitroalkenes are multi-target agents, and thus, it is likely that other important DNA repair targets beyond RAD51 are modified by nitroalkenes, contributing to their anti-cancer effects." (PMID 40196015, 2025). "Indeed, we show that IBC prevents HR-mediated DSB repair by inhibiting the formation of RAD51 foci in cancer cells." (PMID 39887032, 2025). "Given that the more molecular mechanisms of RAD51 regulation in different types of cancer are revealed, the more context-dependent mechanisms should be explored to further improve the efficacy of DNA damage agent-induced cell death in the specific cancer treatment." (PMID 39865088, 2025). "RAD51 has been implicated in PDAC cell proliferation, as well as in cancer progression and metastasis in other tumour types, indicating a correlation between successful DNA repair and the acquisition of cancer hallmarks of an aggressive tumour phenotype." (PMID 40091075, 2025). "For instance, RAD51, known for its role in DNA repair, becomes crucial in the context of cancer, where its expression might be upregulated in response to the heightened DNA repair needs of rapidly dividing tumor cells." (PMID 39744578, 2025). "RAD51 is a central player in the homologous recombination repair pathway and facilitates the repair of DNA double-strand breaks, contributing to radioresistance by allowing cancer cells to repair radiation-induced DNA damage." (PMID 40652278, 2025). "Notably, RAD51 plays a key role in mediating the resistance of cancer cells to PARP inhibitors in triple-negative BC." (PMID 39940796, 2025). "HSF4‐mediated RAD51 expression has not been evaluated in cancer, where elevated RAD51 expression is linked to poor prognosis, but has been demonstrated to counteract the accumulation of cataract‐promoting DNA damage in the lens." (PMID 40457168, 2025). "Moreover, a wide range of cancers show elevated RAD51 expression and RAD51-mediated HR rate, which correlate with reduced overall survival and resistance to DNA damage-inducing chemotherapy and radiotherapy." (PMID 40091075, 2025). "Indeed, RAD51 foci were observed in the cancer cells from BRCA1/2 mutant patients that acquired PARPi resistance." (PMID 39007266, 2024). "RAD51 is therefore a potential target in the therapeutic strategy for cancer." (PMID 38248420, 2024). "Furthermore, the R-loops induced by DNA damage promote RAD51-dependent HR, contributing to the DNA damage resistance of cancer cells." (PMID 38383600, 2024).
cancer (continued). "However, Cur has been found to lower the expression of Rad51, leading to DNA damage in cancer cells." (PMID 38572428, 2024). "Repression of RAD51 expression leads to accumulation of chromatid and chromosome breaks, but RAD51 mutations do not correlate strongly with cancer incidence." (PMID 38530355, 2024). "RAD51 detected 86% of cancers with HRD and 90% with HRR proficiency (HRP)." (PMID 38397209, 2024). "Moreover, RAD51 was reported to be upregulated in several neoplasms and it was responsible for chemoresistance, poor cancer prognosis, as well a higher incidence of metastasis." (PMID 39564119, 2024). "Mouse knockout studies have shown that loss of RAD51 causes a complete block in cellular proliferation; therefore it is likely that cancer cells cannot survive in the absence of RAD51." (PMID 38530355, 2024). "Studies have shown that some cancers with PTEN loss are sensitive to PARP inhibitors, and this may be due to down regulation of Rad51, a critical HR component." (PMID 39085400, 2024). "Notably, carboplatin significantly increased the expression of DNA damage repair-related genes, POLQ and RAD51, in cancer cells." (PMID 38740757, 2024). "Given the pivotal role that Rad51 plays during DNA repair in eukaryotes and particularly in cancer cells, targeting the Hda1-Hsp90 axis could be explored as a new therapeutic approach against cancer." (PMID 38705392, 2024). "RAD51 is considered a therapeutic target for combating cancer drug resistance." (PMID 38892180, 2024). "Remarkably, RAD51 is marked by a paradoxical absence of cancer predisposition due to altered variants, in contrast to its HR partners (mediators and accessory proteins)." (PMID 37190078, 2023). "Given the correlation of RAD51 overexpression with treatment resistance and an aggressive phenotype in many cancers, as well as the therapeutic potential of RAD51 inhibitors, subsequent studies on RAD51 genetic variants may yield clinically valuable results." (PMID 37894339, 2023). "Whereas three pathogenic variants in RAD51 have been reported in four cases of an atypical form of FA (FA-R), no cancer predisposition has been associated with these RAD51 mutations to date (cases reported at <4 months and 13, 23, and 9 years of age)." (PMID 37190078, 2023). "Targeting RAD51 inhibition has demonstrated an antitumor effect in several cancers." (PMID 37175611, 2023). "In addition, several small molecules and peptides inhibiting RAD51 have been developed to increase MM cancer cell sensitivity to doxorubicin or melphalan." (PMID 36967378, 2023). "RAD51 overexpression may result in DNA hyperrecombination, contributing to genomic instability, and might transform normal cells into cancer cells, influencing cancer progression." (PMID 37175611, 2023). "Similarly, association with increased cancer susceptibility has been associated with germline variants of FANCA, FANCM, and FANCR (RAD51), among others." (PMID 38023254, 2023). "The transient formation of R-loops in ALT cancer cells provokes replication stress, but it also signals an early stage of DNA repair by recruiting RAD51, BRCA1, and other repair factors and initiating HR-mediated telomere synthesis induced by DNA strand breaks." (PMID 37046839, 2023). "In addition, our protection analysis unveiled the deficiency of the two cancer-associated mutants, BCDX2 Q133K and C135Y, in RAD51-mediated fork protection." (PMID 37843130, 2023). "Our results and insights on CX3 structure and replication biology advance knowledge of the multiverse of RAD51 paralog functions contributing to BRCAness that may aid an actionable understanding of cancer biology and therapy including PARPi sensitivity." (PMID 37488098, 2023). "The RAD51 genetic analysis of this study suggested that RAD51 genetic alterations might not be the major factor that drives the development of cancers, because the genetic alteration rate of RAD51 in cancers was relatively low." (PMID 35359409, 2022).